SNX9 (sorting nexin 9)
Description:
Involved in endocytosis and intracellular vesicle trafficking, both during interphase and at the end of mitosis. Required for efficient progress through mitosis and cytokinesis. Required for normal formation of the cleavage furrow at the end of mitosis. Plays a role in endocytosis via clathrin-coated pits, but also clathrin-independent, actin-dependent fluid-phase endocytosis. Plays a role in macropinocytosis. Promotes internalization of TNFR. Promotes degradation of EGFR after EGF signaling. Stimulates the GTPase activity of DNM1. Promotes DNM1 oligomerization. Promotes activation of the Arp2/3 complex by WASL, and thereby plays a role in the reorganization of the F-actin cytoskeleton. Binds to membranes enriched in phosphatidylinositol 4,5-bisphosphate and promotes membrane tubulation. Has lower affinity for membranes enriched in phosphatidylinositol 3-phosphate.
Synonyms: SH3PX1; SH3PXD3A; SDP1; WISP
Tractability: Small molecule: a structure with a bound ligand is known; it has a high-quality binding pocket. Antibody: its Gene Ontology location is reachable by antibodies, with high confidence; UniProt places it where antibodies can reach, with medium confidence; the Human Protein Atlas places it where antibodies can reach. PROTAC: UniProt records ubiquitination sites on it; ubiquitination databases record sites on it; its protein half-life has been measured.
Gene: Protein-coding gene on chromosome 6 (157,700,387 to 157,945,077, forward strand). Ensembl gene ENSG00000130340.
Subcellular location: Cytoplasmic vesicle membrane; Cell membrane; Cytoplasmic vesicle, clathrin-coated vesicle; Golgi apparatus, trans-Golgi network; Cell projection, ruffle; Cytoplasm
Subcellular location (Human Protein Atlas): Plasma membrane; Cytosol
Pathways (Reactome):
Vesicle-mediated transport: Clathrin-mediated endocytosis; Golgi Associated Vesicle Biogenesis
Gene Ontology:
Molecular function: 1-phosphatidylinositol binding; Arp2/3 complex binding; cadherin binding; identical protein binding; phosphatidylinositol binding; protein binding; protein homodimerization activity; ubiquitin protein ligase binding
Biological process: cleavage furrow formation; endocytosis; endosomal transport; intracellular protein transport; lipid tube assembly; mitotic cytokinesis; plasma membrane tubulation; positive regulation of GTPase activity; positive regulation of membrane protein ectodomain proteolysis; positive regulation of protein kinase activity; protein-containing complex assembly; receptor-mediated endocytosis; positive regulation of actin filament polymerization; mitotic cell cycle; positive regulation of catabolic process; protein transport; regulation of synaptic vesicle endocytosis
Cellular component: clathrin-coated pit; clathrin-coated vesicle; cytoplasm; cytoplasmic vesicle; cytoplasmic vesicle membrane; cytosol; extracellular exosome; plasma membrane; trans-Golgi network; cuticular plate; Golgi apparatus; presynapse; ruffle
Genetic constraint (gnomAD): Loss-of-function variants: 38 observed, 73.99 expected, observed/expected ratio (o/e) 0.51, 90% interval 0.4 to 0.67. The upper end of that interval is the gene's LOEUF score, 0.67, which puts it in group 2 of 6, group 1 being the genes least tolerant of losing a copy. Missense variants: 512 observed, 678.04 expected, observed/expected ratio (o/e) 0.76, 90% interval 0.7 to 0.81. Synonymous variants: 209 observed, 231.05 expected, observed/expected ratio (o/e) 0.9, 90% interval 0.81 to 1.01.
Homologues: Orthologues: chimpanzee SNX9 (99% identical), macaque SNX9 (99% identical), dog SNX9 (93% identical), guinea pig SNX9 (91% identical), rabbit SNX9 (91% identical), rat Snx9 (91% identical), mouse Snx9 (91% identical), pig SNX9 (90% identical), tropical clawed frog snx9 (75% identical), zebrafish snx9b (65% identical), zebrafish snx9a (57% identical). Paralogues in human: SNX18 (36% identical), SNX33 (34% identical), SNX30 (15% identical), SNX7 (14% identical), SNX1 (13% identical), SNX2 (13% identical), SNX8 (12% identical), SNX4 (12% identical), SNX5 (12% identical), SNX32 (11% identical), SNX6 (10% identical), SNX11 (7% identical), and 3 more.
Diseases named in the same sentence as SNX9 in open-access papers:
SNX9 is named in the same sentence as 33 diseases in open-access papers, as found by Europe PMC text mining. Sharing a sentence is not in itself a finding about the gene and the disease. The quoted sentences say what the papers report.
breast carcinoma (6 papers, 2013 to 2025). "SNX9 has been shown to lower expressed in breast cancer and non-small cell lung cancer in highly advanced stage." (PMID 35715463, 2022). "SNX9 is shown to provoke breast cancer metastasis via modulating RhoGTPase." (PMID 29671787, 2018). "Recently, sorting nexin 9 (SNX9) regulates invadopodia formation and cell invasion in breast cancer cells." (PMID 31443371, 2019). "On the other hand, it has been shown that SNX9, which is closely related to SNX18, is expressed at decreasing levels with cancer progression and in general in tumor tissue, pointing towards its tumor suppressive functions in breast cancer." (PMID 40805149, 2025).
colon cancer (3 papers, 2020 to 2022). "In addition, overexpression of SNX9 has been found in vascular endothelial cells in colon cancer, which was proved to be associated with poor prognosis of colon cancer." (PMID 35715463, 2022). "In addition, SNX9 expression levels differ between colon cancer cell lines, as well as having other varying redundant sorting nexin proteins." (PMID 31947656, 2020).
cyst (2 papers, 2020 to 2022). A sac-like closed membranous structure that may be empty or contain fluid or amorphous material. "Sorting nexin 9 (SNX9) inhibits cell proliferation and cyst development in ADPKD by activating Hippo signaling." (PMID 36483738, 2022). "In contrast, SNX9 silencing in MDCK cells resulted in significant increases in both the percentage of renal cyst formation and cyst diameter compared with those in control cells." (PMID 32974348, 2020).
Diabetes (2 papers, 2021 to 2025). "The SNX9 inhibitor and diabetes groups had similar percentages of closed wound areas (95.1% and 93.0%, respectively)." (PMID 39835574, 2025). "On day 14, the hgMDV+SNX9‐IN group showed significantly more collagen deposition in the regenerated tissue than the diabetes and hgMDV groups, highlighting the effective role of the SNX9 inhibitor in this process." (PMID 39835574, 2025). "Treatment with the SNX9 inhibitor resulted in denser granulation tissue than in the diabetes group." (PMID 39835574, 2025). "In conclusion, this study revealed a significant increase in MDVs during the transition from diabetes to DFU, a process likely regulated by SNX9 in fibroblasts." (PMID 39835574, 2025).
melanoma (2 papers, 2022 to 2023). A malignant, usually aggressive tumor composed of atypical, neoplastic melanocytes. "In this cohort of melanoma patients, the percentage of SNX9+ cells among CD8 T cells before treatment correlated with poor response to ICB." (PMID 36732507, 2023). "So far, our data reveal that the expression levels for clathrin, vimentin, and SNX9 increased during TRPV4 activation induced exocytosis in human melanoma A375 cells." (PMID 35456964, 2022).
Renal cyst (2 papers, 2020 to 2024). A fluid filled sac in the kidney. "We demonstrated that SNX9 activates the Hippo signaling pathway, which attenuated cell proliferation and renal cyst formation and enlargement." (PMID 32974348, 2020). "Accordingly, we concluded that SNX9 inhibits renal cyst formation and enlargement in ADPKD cells." (PMID 32974348, 2020). "The ectopic expression of SNX9 significantly inhibited ADPKD cell proliferation, renal cyst formation and enlargement, whereas these effects were promoted by SNX9 silencing." (PMID 32974348, 2020). "Importantly, the increased renal cyst formation percentage and the diameter enlargement observed in MDCK cells following SNX9 depletion were markedly inhibited by verteporfin treatment." (PMID 32974348, 2020). "Furthermore, we demonstrated that SNX9 interacted directly with YAP and promoted LATS1-mediated YAP phosphorylation, resulting in the cytoplasmic retention of YAP and the transcriptional inactivation of the YAP/TEAD4 complex, which, consequently, retards renal cyst development." (PMID 32974348, 2020).
focal segmental glomerulosclerosis (1 paper, 2017). A renal disorder characterized by sclerotic lesions in the glomeruli. "Finally, an analysis of human glomerular disease biopsy samples demonstrated strong SNX9 expression and co-localization with podocin in samples representative of severe podocyte injury, such as IgA nephropathy with poor prognosis, membranous nephropathy and focal segmental glomerulosclerosis." (PMID 28266622, 2017).
glomerular disease (1 paper, 2017). "In conclusion, we identified SNX9 as a facilitator of podocin endocytosis in severe podocyte injury and demonstrated the expression of SNX9 in the podocytes of both nephropathy model mice and human patients with irreversible glomerular disease." (PMID 28266622, 2017). "We detected strong SNX9 expression and co-localization with podocin in ADR-injected mice and samples from human patients with severe glomerular diseases such as IgAN-poor, MN and FSGS, suggesting a pivotal role for SNX9 in podocin endocytosis under pathological conditions." (PMID 28266622, 2017). "We demonstrate that SNX9 is strongly expressed and co-localizes with podocin in both kidneys from adriamycin (ADR)-injected mice and kidney biopsy samples from human patients with glomerular diseases leading to glomerulosclerosis." (PMID 28266622, 2017).
IgA nephropathy (1 paper, 2017). "In conclusion, we have demonstrated the emergence of SNX9 expression and consequent internalization of podocin via endocytosis in an ADR-induced nephropathy model, as well as in samples from patients with IgA nephropathy with a poor prognosis, MN and FSGS." (PMID 28266622, 2017).
Parkinson disease (1 paper, 2021). A progressive degenerative disorder of the central nervous system characterized by loss of dopamine producing neurons in the substantia nigra and the presence of Lewy bodies in the substantia nigra and locus coeruleus. "For this, we took advantage of the Parkinson’s Disease-related protein Parkin, which stimulates the formation of lysosome-targeted MDVs and, importantly, inhibits the Snx9-dependent pathway in the context of antigen presentation." (PMID 33785738, 2021). "We show that Optic Atrophy 1 (OPA1) and sorting nexin 9 (Snx9)-dependent MDVs are required to target mitochondrial proteins to EVs, while the Parkinson’s disease-related protein Parkin blocks this process by directing damaged mitochondrial content to lysosomes." (PMID 33785738, 2021).
viral infection (1 paper, 2022). "SNX9 is a member of the sorting nexin family involved in intracellular trafficking and clathrin-mediated endocytosis, yet its role in viral infection has not been reported." (PMID 35516420, 2022).
ZIKV infection (1 paper, 2023). "Increased mRNA expression levels of ISG15 upon Snx6 and/or Snx9 knockdown during ZIKV infection were observed, suggesting that disruption of MDV formation during ZIKV infection affects the host antiviral response in JEG-3 cells." (PMID 37781396, 2023).
tumor (11 papers, 2019 to 2025). "In summary, we provide evidence that a loss of SNX9 in primary tumor-antigen specific T cells reduces activation in the context of intact CD28-CD80/86 signaling." (PMID 36732507, 2023). "Here the authors develop a human ex vivo exhaustion model and, based on a CRISPR-Cas9 screen, identify SNX9 as a regulator of T cell exhaustion, showing that SNX9 knockout is associated with improved T cell function and anti-tumor activity in preclinical cancer models." (PMID 36732507, 2023). "While SNX9 has been identified in expression analyses of tumor-infiltrating T cells before, its role in T cell exhaustion has remained unexplored." (PMID 36732507, 2023). "Within the CD8 tumor-infiltrating T cells cluster, SNX9 expression was negatively correlated with the expression of central-memory and progenitor markers, CCR7 and TCF7." (PMID 36732507, 2023). "The in vivo anti-tumor efficacy of adoptively transferred murine TCR transgenic T cells was improved by Snx9 KO, which correlated with increased effector-memory-like differentiation, enhanced chemokine expression, and elevated IFNγ serum levels." (PMID 36732507, 2023). "Our findings highlight that targeting SNX9 is a strategy to prevent T cell exhaustion and enhance anti-tumor immunity." (PMID 36732507, 2023). "SNX9 knockout enhances memory differentiation and IFNγ secretion of adoptively transferred T cells and results in improved anti-tumor efficacy of human chimeric antigen receptor T cells in vivo." (PMID 36732507, 2023). "In summary, SNX9 KO alleviates exhaustion, increases chemoattraction, and prolongs IFNγ secretion of tumor-specific T cells." (PMID 36732507, 2023). "Although no study revealed the roles of SNX21 in cancer, its family genes, such as SNX1, SNX5 and SNX9 were suggested to be tumor suppressor related." (PMID 31565549, 2019). "NY-ESO-1 TCR-T cells generated from CD8+ T cells revealed that Subsequent investigations revealed that sorting nexin 9 (SNX9) regulates both T cell exhaustion (PD1+) and cytotoxic function (CD107a+), with SNX9 knockout enhancing T cell activation signals and anti-tumor potential." (PMID 39538305, 2024). "We discovered that while SNX9 KO reduces T cell activation, it also enhances anti-tumor immunity." (PMID 36732507, 2023). "Notably, we observed a similar improvement in anti-tumor efficacy by Snx9 KO when OTI cells were transferred to (immunodeficient) NSG mice with MC38-OVA tumors." (PMID 36732507, 2023). "Therefore, this study provides evidence towards the tumor-suppressor roles of SNX9 and also indicates towards its potential in the prevention of liquid cancers, among others, in an ADAM9-dependent manner." (PMID 36612066, 2022). "A decrease in nexin 9 (SNX9) in invadopodia in NSCLC is correlated with tumor invasiveness." (PMID 33262947, 2020). "SNX9 protein is highly expressed in tumor and tumor-endothelial cells of human CRC tissues, suggesting that SNX9 may also function in cell invasion/migration in the epithelial cells of CRCs, in addition to its novel function in angiogenesis of the endothelial cells." (PMID 31443371, 2019). "We thereby discover that a knockout of sorting nexin-9 (SNX9) improves T cell effector functions and memory differentiation, translating into enhanced anti-tumor efficacy of adoptively transferred T cells including CAR T cells in vivo." (PMID 36732507, 2023). "We wanted to better understand how Snx9 KO improves anti-tumor efficacy in vivo, and, therefore, characterized OTI number and phenotype in MC38-OVA tumor-bearing mice." (PMID 36732507, 2023). "The removal of tumor suppressor genes sorting nexin 9 (SNX9) and synaptojanin 2 (SYNJ2) in the 6q25.3 location of chromosome 6 disturbs their functions, including the regulation of cell migration from the primary tumor site to distant organs and the inhibition of tumor development." (PMID 34203272, 2021).
tumor (continued). "This suggests that while Snx9 KO OTI cells promote the recruitment of other immune cells, Snx9 KO OTI cells can directly mediate anti-tumor effects in NSG mice independent of an intact endogenous immune system." (PMID 36732507, 2023).
cancer (10 papers, 2009 to 2026). A tumor composed of atypical neoplastic, often pleomorphic cells that invade other tissues. "In summary, our findings suggest that SNX9 fine-tunes T cell activation and is a potential target to improve the efficacy of cellular immunotherapies in cancer patients." (PMID 36732507, 2023). "SNX9 promotes cancer cell invasion and metastasis via endocytic pathways." (PMID 41487280, 2026). "Additionally, SNX9 mediated the endocytosis of MT1-MMP metalloproteinase, a crucial component for extracellular matrix degradation, thereby suggesting a possible role of SNX9 in regulating cancer cell invasiveness." (PMID 36612066, 2022). "Meanwhile, SNX9 expression is increased in metastases, and could promote metastasis by enhancing cancer cell invasion." (PMID 27655699, 2016).
infection (6 papers, 2018 to 2023). The state of being infected such as from the introduction of a foreign agent such as serum, vaccine, antigenic substance or organism. "SNX9 has been implicated in both the entry and infection of Salmonella and pedestal formation by EPEC and related EHEC." (PMID 29727463, 2018). "Given that SNX9 is transiently recruited to C. trachomatis entry foci, we next investigated the possible roles for SNX9 during infection." (PMID 29727463, 2018). "Therefore, we further investigated the importance of MDVs during PRV infection in JEG-3 cells via Snx6- and Snx9-specific siRNA transfection individually or in combination prior to infection." (PMID 37781396, 2023). "In previous work, we have confirmed that EspF interacts with SNX9 and N-WASP, confirming its critical role during infection." (PMID 34575120, 2021). "As the membrane-scission protein dynamin interacts with SNX9, we examined the structure of early C. trachomatis-containing vacuoles at 3 hours post infection of HAP1 wild type and SNX9-/- by cryo-EM tomography." (PMID 29727463, 2018). "AGO4, SNX9, SCD were also downregulated after infection with MA08." (PMID 34671358, 2021).
kidney diseases (2 papers, 2017 to 2020). "Of note, recent studies have uncovered the vital role played by SNX9 in the pathogenesis of renal diseases." (PMID 32974348, 2020). "Taken together, our findings provided novel insights into the role played by SNX9 during ADPKD pathogenesis and may reveal novel therapeutic approaches for ADPKD and related kidney diseases." (PMID 32974348, 2020).
SNX9 also shares sentences with these, for which no sentence is quoted: colorectal cancer (2 papers); Lowe syndrome (2); acute pancreatitis (1); asthma (1); atherosclerosis (1); autosomal dominant polycystic kidney disease (1); bacterial infection (1); Dent-2 disease (1); Down syndrome (1); Insulin resistance (1); membranous nephropathy (1); Nephropathy (1); non-small cell lung carcinoma (1); Obesity (1); perivascular epithelioid cell neoplasms (1); triple-negative breast carcinoma (1); Whipple disease (1).